ITGA2B (integrin subunit alpha 2b)
Diseases named in the same sentence as ITGA2B in open-access papers (continued):
Sharing a sentence is not in itself a finding about the gene and the disease.
infection (35 papers, 2010 to 2025). The state of being infected such as from the introduction of a foreign agent such as serum, vaccine, antigenic substance or organism. "To our knowledge, we are the first to describe a possible association between higher susceptibility to infection with MAP and higher expression of ITGA2B on bovine PBMC." (PMID 36295826, 2022). "Moreover, as we only included animals with clear infection status to our study, testing of PBMC from animals which could not clearly be differentiated into negative or positive by current diagnostic tests should be analyzed for ITGA2B expression." (PMID 36295826, 2022). "Two of these genes, ITGB3 (logFC of 3.77) and ITGA2B (logFC of 1.58), were upregulated in the cells challenged with ETEC, while this upregulation was abolished by pretreating cells with EPS before infection." (PMID 32234079, 2020). "Although, most shared altered host proteins between both BVDV biotypes showed the same type of change, integrin alpha 2b (ITGA2B) and integrin beta 3 (ITGB3) were down- regulated by ncp BVDV and up- regulated by cp BVDV infection." (PMID 20946620, 2010). "Interestingly, ITGA2B and integrin beta 3 (ITGB3) were found to be downregulated in PBMCs in infection by non-cytopathic bovine viral diarrhea virus (ncp BVDV) and upregulated by the cytopathic biotype (cp BVDV) in proteomic studies." (PMID 28475627, 2017).
cardiovascular disease (7 papers, 2010 to 2025). "The content of ITGA2B in peripheral blood and its gene polymorphisms are closely related to the severity of cardiovascular disease." (PMID 40198259, 2025). "Aspirin-associated gene ITGA2B correlates with smoking status of patients with cardiovascular disease." (PMID 35096131, 2022). "Several studies in recent years have shown that ITGA2B is an important predictor of cardiovascular disease." (PMID 40198259, 2025).
inflammation (2 papers, 2013 to 2025). Aberrant reaction of the microcirculation characterized by movement of fluid and leukocytes from the blood into extravascular tissues. "Our study uncovers a previously unknown role of ITGA2B in inducing cardiac inflammation by enhancing the transcriptional activity of NF-κB in heart tissues, which aggravates chronic hypoxia-induced cardiac overload." (PMID 40198259, 2025).
autosomal recessive disease (1 paper, 2014). Autosomal recessive form of disease. "As GT is an autosomal recessive disease, patients are mostly compound heterozygotes for ITGA2B or ITGB3 mutations in the absence of consanguinity." (PMID 25539746, 2014).
metabolism disorders (1 paper, 2025). "Functionally, we found that aberrant upregulation of ITGA2B resulted in metabolism disorders, increased secretion of inflammatory cytokines, and dysregulation of cardiac structure and function under hypoxic conditions." (PMID 40198259, 2025).
ITGA2B also shares sentences with these, for which no sentence is quoted: diabetes (14 papers); myocardial infarction (13); immune thrombocytopenia (10); melanoma (10); thalassemia (8); atherosclerosis (6); hemorrhage (6); viral infection (6); aneurysm (5); endothelial dysfunction (5); ischemic stroke (5); acute myeloid leukemia (4); acute myocardial infarction (4); asthma (4); dengue (4); Hyperglycemia (4); ovarian carcinoma (4); prostate carcinoma (4); acute megakaryoblastic leukemia (3); bacterial infection (3); colorectal cancer (3); Coma (3); hematological malignancies (3); hypercoagulable (3); intracerebral hemorrhage (3); intracranial hemorrhage (3); liver disease (3); myelodysplastic syndrome (3); psoriasis (3); Thrombocytosis (3).
A further 134 diseases each share a sentence with ITGA2B in 2 papers or fewer.